RNF5 (ring finger protein 5)
Diseases named in the same sentence as RNF5 in open-access papers (continued):
Sharing a sentence is not in itself a finding about the gene and the disease.
breast carcinoma (continued). "When breast cancer cells are exposed to paclitaxel chemotherapies, which induce an ER stress environment, SLC1A5 is ubiquitinated by RNF5 (an important E3 ubiquitin ligase related to ER-stress-related protein regulation)." (PMID 37190313, 2023). "Given that EphA2 can interact with HER2 (also named ErbB2) and cooperate with HER2 to activate ERK signaling, we concluded that RNF5 inhibition decreases ERK and Akt activation through the increase in the EphA2 level in HER2-negative breast cancer cells." (PMID 37816703, 2023). "As a consequence, low RNF5 expression with high EphA2 expression exhibits tumor-suppressive properties and increased survival in estrogen receptor-positive HER2-negative breast cancers." (PMID 37816703, 2023). "Acetylation of PHGDH at the Lys-58 site can prevent the interaction between RNF5 and PHGDH, thereby stabilizing PHGDH and promoting the proliferation of breast cancer cells." (PMID 37190313, 2023). "RNF5 regulates the turnover of SLC1A5 and SLC38A2 in about 30% of breast cancer patients that are responsive to taxanes-based therapies, which is associated with better prognosis." (PMID 26425657, 2015). "Similarly, the E3 ligase RNF5 directly interacted with EphA2 and induced EphA2 ubiquitination and degradation in HER2-negative breast cancer cells, thereby suppressing EphA2 tumor-suppressive functions in this neoplasia." (PMID 39596256, 2024). "Thus we conclude that RNF5 limits EphA2 level and tumor-suppressive function to facilitate tumor formation of HER2-negative breast cancers." (PMID 37816703, 2023). "Consequently, RNF5 inhibition increases the adhesion and decreases the migration of HER2-negative breast cancer cells, and RNF5 silencing suppresses the growth of xenograft tumors derived from ER-positive, HER2-negative breast cancer cells with increased EphA2 expression and altered phosphorylation." (PMID 37816703, 2023). "Therefore, our studies indicate that RNF5 reduces the stability and cell surface distribution of EphA2 and maintains the balance of its phosphorylation to inhibit its tumor-suppressive function in HER2-negative breast cancers." (PMID 37816703, 2023).
melanoma (13 papers, 2019 to 2025). A malignant, usually aggressive tumor composed of atypical, neoplastic melanocytes. "High RNF5 expression in neuroblastoma and melanoma is associated with improved patient survival, suggesting a tumor-suppressive role." (PMID 40370434, 2025). "We also assessed the association between RNF5 expression levels and overall survival of melanoma patients included in the publicly available dataset GSE65904." (PMID 35406574, 2022). "Here the authors show that Rnf5 deficiency potentiates immune response against melanoma via altered microbiota, and isolate bacterial strains that confer the same phenotype to wild type mice." (PMID 30940817, 2019). "Genetic deficiencies in mice and bone marrow chimeras have unveiled the integral role of ring-finger protein 5 (RNF5), an E3 ubiquitin ligase, in melanoma immune surveillance." (PMID 38617537, 2024). "In neuroblastoma and in melanoma patients, RNF5 expression is correlated with better disease outcome." (PMID 38139010, 2023). "To confirm that RNF5 is a candidate target for the treatment of NB and melanoma, we evaluated its expression in a panel of human NB (SH-SY5Y, SK-N-SH, IMR-32, HTLA-230) and human melanoma (MZ2-MEL, A2058, G-361, SK-MEL-28) cell lines by western blot." (PMID 35406574, 2022). "The therapeutic effect of Analog-1, an RNF5 pharmacological activator, was investigated on in vitro and in vivo neuroblastoma and melanoma models." (PMID 35406574, 2022). "In this study, we evaluate the biological effects of Inh-2 and Analog-1 in NB and melanoma cell lines as well as normal cells expressing RNF5." (PMID 35406574, 2022). "The aim of this study was to elucidate the controversial role of RNF5 in neuroblastoma and melanoma, two neuroectodermal tumors of infancy and adulthood, respectively." (PMID 35406574, 2022). "Here we provide evidence that a novel RNF5 activator, Analog-1, exerted a potent anti-tumor effect in in vitro and in vivo NB and melanoma models through down-regulation of cell metabolism, inhibition of proliferation and induction of apoptosis." (PMID 35406574, 2022). "This study is of high translational relevance since it validates RNF5 as an innovative drug target and supports the development of novel therapies for neuroblastoma and melanoma patients in order to ameliorate their clinical outcome." (PMID 35406574, 2022). "The potential therapeutic effect of novel pharmacological modulators of RNF5 was also investigated on in vitro and in vivo experimental NB and melanoma models." (PMID 35406574, 2022). "We next evaluated the effect of small drug-like compounds, recently defined as inhibitors and activators of RNF5, in two representative NB and melanoma cell lines, SH-SY5Y and MZ2-MEL, respectively." (PMID 35406574, 2022). "Here, we demonstrate that high RNF5 expression in both NB and melanoma patients correlates with a better prognostic outcome in terms of overall and event free survival." (PMID 35406574, 2022). "Prophylactic transfer of cecal contents from Rnf5-/- mice prevented melanoma growth in GF mice partially by increasing the frequency of TILs and improving antitumor cytokine response." (PMID 36726985, 2022). "In this study, we demonstrated that RNF5, a ubiquitin ligase involved in the degradation of misfolded proteins, was expressed in neuroblastoma and melanoma patients and positively correlated with better outcome." (PMID 35406574, 2022). "A lower number of Lactobacillus was observed in melanoma-bearing Rnf5-/- mice than melanoma-bearing WT mice." (PMID 36726985, 2022). "In both neuroblastoma and melanoma patients the high expression of RNF5 correlated with a better prognostic outcome." (PMID 35406574, 2022). "RNF5 gene levels are evaluated in publicly available datasets reporting the gene expression profile of melanoma and neuroblastoma primary tumors at diagnosis." (PMID 35406574, 2022).
melanoma (continued). "Transfer of 11 bacterial strains, including B. rodentium, enriched in Rnf5−/− mice, establishes anti-tumor immunity and restricts melanoma growth in WT germ free mice." (PMID 33708214, 2021). "CRISPR/Cas9-mediated RNF5 deletion in mouse melanoma cells markedly reduced ER-stress-mediated activation of inositol-requiring enzyme 1α (IRE1α) as seen by the level of sXBP1, key UPR components." (PMID 30940817, 2019). "Altered UPR signaling, exemplified in Rnf5−/− mice, coincides with altered gut microbiota composition and anti-tumor immunity to control melanoma growth." (PMID 30940817, 2019). "Given the controversial pathophysiological role of RNF5 in cancer, we extended the study of its functional expression to neuroblastoma (NB) and melanoma, which represent two neuroectodermal tumors of infancy and adulthood, respectively, with the same embryonal origin and poor prognosis." (PMID 35406574, 2022). "ABX could reverse the inhibitory effects of Rnf5 deletion on melanoma growth, implying that the gut microbiota played an important role in regulating antitumor immunity in Rnf5-/- mice." (PMID 36726985, 2022). "Consequently, the suppressive effect of Rnf5 depletion on melanoma growth was attenuated after co-housing." (PMID 36726985, 2022). "Overall these findings validate RNF5 as a drug target for neuroectodermal tumors, and Analog-1 as a promising small drug to progress towards full preclinical development, paving the way to future clinical trials for NB and melanoma patients." (PMID 35406574, 2022). "Their data demonstrated that RNF5 loss, linked with an altered UPR signaling, coincided with variations in gut microbiota composition, activation of antitumor immunity, and consequently, efficient melanoma growth inhibition." (PMID 33800394, 2021). "To determine whether Rnf5−/− mice exhibit altered antitumor immune response, we evaluated the growth of a series of mouse melanoma cell lines injected subcutaneously into the flank of syngeneic Rnf5−/− C57BL/6 mice obtained by crossing of Rnf5 heterozygotes." (PMID 30940817, 2019). "Co-housing of Rnf5−/− and WT mice abolishes the anti-tumor immunity and tumor inhibition phenotype, whereas transfer of 11 bacterial strains, including B. rodentium, enriched in Rnf5−/− mice, establishes anti-tumor immunity and restricts melanoma growth in germ-free WT mice." (PMID 30940817, 2019). "Thus, RNF5 may represent a possible target for neuroblastoma and melanoma treatment, and considering the homology with RNF185, the latter ligase may represent a possible focus for a therapeutic strategy for these cancers as well." (PMID 38139010, 2023). "Moreover, Bacteroides rodentium, one of the bacterial strains enriched in Rnf5-/- mice, could elicit antitumor immunity and inhibit melanoma development in GF mice." (PMID 36726985, 2022). "Given the previous indication that RNF5 promoted ubiquitination and degradation of glutamine transporters, which are aberrantly folded following chemotherapy-induced ER stress, we investigated the effect of Analog-1 on glutamine metabolism of NB and melanoma cell lines." (PMID 35406574, 2022). "While in line with the finding in Rnf5−/− mice, these findings suggest a relationship between ER stress markers and response to immunotherapy, thereby indicating the possible use of reduced sXBP1 and BiP expression as markers for melanoma patients responsiveness to immunotherapy." (PMID 30940817, 2019). "Notably, rnf5−/− mice present an enhanced antitumor response, which is coupled with greater recovery and function of CD8+ lymphocytes in melanoma tumors." (PMID 35406574, 2022). "Analogously, RNF5 activation slows the proliferation of melanoma cells, which, irrespective of their oncogenic background, depend on glutamine to grow." (PMID 35406574, 2022).
melanoma (continued). "Our results demonstrate that Analog-1 specifically inhibited the viability of NB and melanoma cell lines without any cytotoxic effect on fibroblasts, suggesting that activation of RNF5 represents a potential anti-tumor treatment strategy." (PMID 35406574, 2022). "Melanoma growth in Rnf5−/− mice that were co-housed with WT mice, was no longer inhibited, again pointing to the importance of gut microbiota components present in Rnf5−/− for limiting tumor growth." (PMID 30940817, 2019). "Therefore, despite the low RNF5 expression observed also in melanoma patients with poor clinical outcome, the lack of significance did not allow to confirm its prognostic impact in melanoma tumors." (PMID 35406574, 2022). "We can speculate that the lack of effect of Inh-2 on NB and melanoma cell lines could be due to their high-proliferation rate, which cannot be further increased by RNF5 inhibition." (PMID 35406574, 2022).
cystic fibrosis (7 papers, 2015 to 2023). Autosomal recessive disorder caused by pathogenic variants in the CFTR gene (cystic fibrosis transmembrane conductance regulator), which encodes a chloride and bicarbonate channel expressed in epithelial cells, and follow the diagnosis criteria. "We examined the association between the 8.1 ancestral haplotype and delayed colonization in Cystic Fibrosis, postulating that downregulation of RNF5 expression is the likely causal mechanism." (PMID 31746734, 2019). "Associations between HLA-type eQTLs, RNF5 expression and Cystic Fibrosis." (PMID 31746734, 2019). "More recently, RNF5 has been described as a quality control protein in the ER where it contributes to the clearance of misfolded proteins, including the F508del mutant cystic fibrosis transmembrane conductance regulator (CFTR)." (PMID 35406574, 2022). "However, while these studies have focused on the potential use of RNF5 inhibitors in the treatment of cystic fibrosis, limited research to date has explored their application in antiviral therapy." (PMID 38250078, 2023). "Interestingly, the association of RNF5 was consistent with its function as a regulator of the CFTR protein and suggested role in cystic fibrosis." (PMID 31746734, 2019). "RNF5 is an E3 ubiquitin protein ligase, and RNF5-KD significantly reduces AMFR-mediated ubiquitinylation of CFTR, a transmembrane conductance regulator in cystic fibrosis." (PMID 35741332, 2022). "However, unlike SORDD1, which suppressed Rh1G69D–associated retinal degeneration, genetic and pharmacological inhibition of RNF5 in vivo attenuates intestinal pathological phenotypes in a mouse model of cystic fibrosis without blocking degradation of CFTRΔF508." (PMID 33137101, 2020).
acute myeloid leukemia (4 papers, 2021 to 2025). Acute myeloid leukemia (AML) is a group of neoplasms arising from precursor cells committed to the myeloid cell-line differentiation. "Recent work has implicated the overexpression of RNF5 in acute myeloid leukemia (AML)." (PMID 39851497, 2025). "In contrast, in acute myeloid leukemia and hepatocellular carcinoma, high expression of RNF5 correlated with poor prognosis." (PMID 35406574, 2022). "A recent study also showed that RNF5 inhibition decreased the development and progression of acute myeloid leukemia (AML)." (PMID 36656913, 2023). "Recently, the tumor-promoting functions of RNF5 in the development and survival of acute myeloid leukemia (AML) have been revealed." (PMID 36656913, 2023).
neuroblastoma (4 papers, 2022 to 2025). Neuroblastoma (NB) is the most common solid, extracranial childhood tumor. "Furthermore, RNF5 overexpression in high-risk neuroblastoma patients at diagnosis suggest its role as potential druggable target." (PMID 35406574, 2022). "Analog-1 is a pharmacological activator of RNF5, and treatment of neuroblastoma and neuroblastoma cell lines reduces their viability." (PMID 38139010, 2023). "In light of this evidence, it is conceivable that RNF5 exerts a significative anti-neuroblastoma effect by reducing the intracellular content of glutamine likely through degradation of its transporters." (PMID 35406574, 2022).
cardiac hypertrophy (3 papers, 2022 to 2026). "After pathological stimulation, RNF5 deficiency significantly aggravates pathological cardiac hypertrophy, inflammatory response, and fibrosis, while overexpression of RNF5 has the opposite effects." (PMID 36270989, 2022). "The loss-of-function research demonstrated that RNF5 deficiency exacerbated cardiac hypertrophy, whereas gain-of-function studies revealed that overexpression of RNF5 had opposite effects." (PMID 36270989, 2022). "RNF5 inhibits the development of cardiac hypertrophy by targeting STING and promoting its K48- linked ubiquitination-mediated degradation." (PMID 36270989, 2022). "Collectively, these data suggest that RNF5 alleviates pathological cardiac hypertrophy through K48-linked ubiquitination and proteasomal degradation of STING." (PMID 36270989, 2022). "Further studies showed that RNF5 inhibited cardiac hypertrophy by promoting STING degradation through K48-linked polyubiquitination." (PMID 36270989, 2022). "To investigate whether RNF5 is involved in the regulation of cardiac hypertrophy, we constructed RNF5 gene knockout (KO) mice for the loss-of-function experiments." (PMID 36270989, 2022). "Taken together, these results suggest that RNF5 deficiency could activate signaling pathways and genes associated with cardiac hypertrophy." (PMID 36270989, 2022). "In conclusion, our study suggests that RNF5 is one of the negative regulators of pathological cardiac hypertrophy." (PMID 36270989, 2022). "We constructed cellular and animal models of cardiac hypertrophy and found that the expression of RNF5 was increased in these models." (PMID 36270989, 2022). "To explore the role of RNF5 in the development of cardiac hypertrophy and heart failure, we treated neonatal rat cardiomyocytes (NRCMs) with phenylephrine (PE) to induce cardiomyocyte hypertrophy in vitro." (PMID 36270989, 2022). "We further investigated the molecular mechanism of RNF5 in the development of pathological cardiac hypertrophy." (PMID 36270989, 2022). "RT-PCR, WB, and immunofluorescence confirmed that overexpression of STING abolished the regulation of RNF5 in cardiac hypertrophy." (PMID 36270989, 2022). "In this study, we found the expression of RNF5 was increased in the hearts of mice with pathological cardiac hypertrophy." (PMID 36270989, 2022). "In this study, we find that RNF5 expression is upregulated in animal and cellular models of cardiac hypertrophy." (PMID 36270989, 2022). "Additionally, RNF5 has been found to suppress the development of pathological cardiac hypertrophy by potentiating the degradation of STING in cardiac myocytes, suggesting a potential treatment strategy for this condition." (PMID 38250078, 2023). "Rescue experiments showed that overexpression of STING could attenuate the effect of RNF5 on alleviating cardiac hypertrophy." (PMID 36270989, 2022). "In this study, we revealed the function of RNF5 in pathological cardiac hypertrophy." (PMID 36270989, 2022). "STING aggravated pathological cardiac hypertrophy after PE treatment, while RNF5 could promote STING degradation through K48-linked polyubiquitination, thus alleviating cardiac hypertrophy." (PMID 36270989, 2022). "We found that overexpression and inhibition of RNF5 could significantly inhibit and promote myocardial hypertrophy induced by PE stimulation, respectively." (PMID 36270989, 2022). "In conclusion, our results suggest that RNF5 may act as a promising therapeutic target in pathological cardiac hypertrophy." (PMID 36270989, 2022). "Altogether, the increased expression of RNF5 in cardiac hypertrophy samples suggests that RNF5 may be involved in the pathogenesis of cardiac hypertrophy." (PMID 36270989, 2022). "To explore the potential mechanism of RNF5 regulating cardiac hypertrophy, we used IP-MS to screen out candidate proteins that might bind to RNF5." (PMID 36270989, 2022).
cardiac hypertrophy (continued). "We also observed that RNF5 is involved in fibrosis and inflammation in cardiac hypertrophy, but whether RNF5 is involved by directly modulating the function of other cell types in the heart or by regulating cardiomyocyte paracrine function requires further study." (PMID 36270989, 2022). "Therefore, our study suggests that targeting RNF5 may be a promising strategy for the treatment of pathological cardiac hypertrophy." (PMID 36270989, 2022). "Therefore, we defined RNF5 as importantly regulated signaling for cardiac hypertrophy." (PMID 36270989, 2022). "However, current studies on RNF5 have mainly focused on tumor and innate immune responses, and the role of RNF5 in pathological cardiac hypertrophy remains largely unknown." (PMID 36270989, 2022). "However, the potential association between RNF5 and pathological cardiac hypertrophy has not been explored." (PMID 36270989, 2022). "Recent studies have shown that RNF5 promotes the degradation of STING, suggesting it as a potential target for treating pathological conditions such as cardiac hypertrophy." (PMID 38250078, 2023). "We further explored the roles of RNF5 and STING in heart and NRCMs, and the results verified that STING expression was increased in pathological cardiac hypertrophy." (PMID 36270989, 2022). "To explore whether the function of RNF5 regulated cardiac hypertrophy depending on STING, we overexpressed RNF5 and STING, respectively, or simultaneously in NRCMs." (PMID 36270989, 2022). "Our results confirmed the role of RNF5 in regulating cardiac hypertrophy by using RNF5 knockout mice, but we did not perform RNF5 overexpression in vivo, which would better verify our results." (PMID 36270989, 2022). "However, the role of RNF5 in cardiac hypertrophy has not been reported." (PMID 36270989, 2022).